PAICS (phosphoribosylaminoimidazole carboxylase and phosphoribosylaminoimidazolesuccinocarboxamide synthase)
Diseases named in the same sentence as PAICS in open-access papers (continued):
Sharing a sentence is not in itself a finding about the gene and the disease.
tumor (27 papers, 2008 to 2025). "We further explored the detailed mechanism underlying PAICS‐mediated promoting roles in tumor cell proliferation and survival." (PMID 38463398, 2024). "By contrast, in the later stages of tumor progression, PAICS expression appeared to be diminished by genetic loss of chromosome 4q, correlating with poor prognosis." (PMID 33596246, 2021). "In conclusion, this study suggest that PAICS expression is downregulated during tumor progression mainly due to chromosome 4q loss particularly in microsatellite stable but chromosomally unstable tumors." (PMID 33596246, 2021). "Previous studies have revealed that PAICS plays an important role in various tumours and is associated with tumour proliferation and metastasis." (PMID 34173716, 2021). "Importantly, PAICS deficiency impairs DNA repair and increases tumor cell sensitivity to DNA-damaging agents like cisplatin." (PMID 40699765, 2025). "Moreover, PAICS knockdown causes a reduction in tumor growth and metastasis in mouse xenograft models." (PMID 37172090, 2023). "Since arm-level deletions can cause co-suppression of multiple neighboring genes to synergistically contribute to tumor progression, functional roles of 4q loss might differ from those arising from PAICS downregulation." (PMID 33596246, 2021). "Consequently, PAICS expression declined in tumors that exhibited loss of chromosome 4q, demonstrating the coincidence of chromosome 4q loss and PAICS downregulation during tumor progression." (PMID 33596246, 2021). "PAICS protein levels were significantly elevated in tumor samples revealed by IHC staining in patients with adenocarcinoma." (PMID 40428391, 2025). "Purine biosynthesis, regulated by PAICS, plays a key role in tumor progression and therapy resistance." (PMID 40699765, 2025). "Among in vivo studies in mice, the authors confirmed that knockdown of PAICS significantly inhibited tumor growth." (PMID 40428391, 2025). "PAICS’ role in purinosome assembly and its regulation of nucleotide synthesis and tumor proliferation makes it a potential therapeutic target." (PMID 40699765, 2025). "Functional validation confirmed that PAICS knockdown inhibited tumor cell proliferation and migration, and increased sensitivity to AZD6482 and imatinib." (PMID 40699765, 2025). "Taken together, these results demonstrated the critical role of PAICS in tumor progression, suggesting that PAICS is a potential biomarker for predicting the prognosis of tumor patients." (PMID 38463398, 2024). "PAICS promotes tumor cells proliferation and migration, whereas the knockdown of PAICS leads to tumor cell cycle arrest and apoptosis." (PMID 38463398, 2024). "We used the TIMER2 to study the differential expression of PAICS between tumor and adjacent normal tissues for tumors represented in the TCGA repository." (PMID 38463398, 2024). "The volumes of tumor in PAICS‐knockdown groups were significantly smaller, and the weights were significantly lower than those in the control group." (PMID 38463398, 2024). "At the same time, PAICS level were related to tumor metastasis, EGFR status and gender in NSCLC patients based on TCGA database (left), whereas uncorrelated with tumor metastasis, EGFR status and gender from microarray analysis (right)." (PMID 38463398, 2024). "The effect of PAICS on the tumor in vivo was further evaluated by establishing a subcutaneous xenograft tumor model in immunodeficient mice using PAICS‐knockdown and the control H1299 cells." (PMID 38463398, 2024). "As expected, tumor growth was dramatically slower in two PAICS‐knockdown groups (shPAICS#1, shPAICS#3) compared with the control group (shNC)." (PMID 38463398, 2024). "In this study, our focus was to assess the expression and relationship between DYRK3 and PAICS in human tumor xenograft samples with varying degrees of radioresistance and radiosensitivity." (PMID 38139175, 2023).
tumor (continued). "Immunofluorescence results further demonstrated that oe-PAICS induced the EMT of tumor cells, while miR-4731-5p mimic countered this effect." (PMID 35379785, 2022). "There was an increase in tumor volume and weight following PAICS overexpression, while additional treatment with miR-4731-5p agomir reversed these trends." (PMID 35379785, 2022). "The preferentially expressed phosphoribosylaminoimidazole carboxylase (PAICS) is the common tumor promoter in LUAD and can be activated by promoter DNA hypomethylation." (PMID 36523974, 2022). "Given the functional mechanism and carcinogenic potential of CCNB1, CDK1, and PAICS miRNAs, these three genes' upstream miRNAs ought to be tumor suppressive." (PMID 36081668, 2022). "The present study unexpectedly found a decreasing trend of PAICS expression along with tumor progression." (PMID 33596246, 2021). "In conclusion, our results suggest that PAICS expression is downregulated during tumor progression due to genetic deletion of chromosome 4q in microsatellite stable but chromosomally unstable tumors." (PMID 33596246, 2021). "Despite upregulated PAICS levels in tumor compared to those of normal mucosa, we found a decreasing trend of PAICS expression during tumor progression and metastasis." (PMID 33596246, 2021). "As expected, tumor growth was dramatically slower in the PAICS-knockdown group (shPAICS) compared with the control group (shCON)." (PMID 32632107, 2020). "The effect of PAICS on tumor growth in vivo was further evaluated by establishing a subcutaneous xenograft tumor model in nude mice using PAICS-knockdown or the control AGS cells." (PMID 32632107, 2020). "PAICS is required for tumor growth and metastasis, and PAICS knockdown decreases the dissemination of CRC cells to liver and bone." (PMID 32218208, 2020). "HCT116p53-null cells with stable PAICS knockdown showed that tumor weights were lowered by 46% with PAICS shRNA1 and 36% with PAICS shRNA2 compared with the NT shRNA controls." (PMID 32218208, 2020). "At 28 days, for mice injected with PAICS knockdown cells, there was a reduction in luminescence intensity, suggesting a decreased dissemination of tumor cells to liver and bone as compared to mice injected with cells transfected with control shRNA." (PMID 32218208, 2020). "In mice, the depletion of PAICS in CRC cells led to reduced tumor growth and metastatic cell dissemination to the liver, lungs, and bone." (PMID 32218208, 2020). "Through a functional yeast survival screen of tumor-derived cDNA libraries, PAICS was shown to be overexpressed in certain tumor types and capable of suppressing apoptosis in human cells." (PMID 30097015, 2018). "We established glutamine-mediated induction of PPAT and PAICS as an important metabolic event for increased expression of these genes during lung oncogenesis, which in turn enhances tumor-specific pyruvate kinase activity." (PMID 26140362, 2015). "Mechanistically, we highlight PAICS as a key metabolic driver that may promote tumor progression and immune modulation." (PMID 40699765, 2025). "PAICS expression in subcutaneous tumor exhibited a significant decrease in PAICS knockdown group." (PMID 38463398, 2024). "A genome‐wide CRISPR/Cas9 screen has identified the enzyme phosphoribosylaminoimidazole carboxylase/phosphoribosylaminoimidazole succinocarboxamide synthetase (PAICS), which is vital in de novo purine biosynthesis and tumor development, as a potential drug target for EGFR wild‐type NSCLC." (PMID 38463398, 2024). "PAICS protein significantly elevated in tumor specimens revealed by IHC staining (right)." (PMID 38463398, 2024). "We explored the PAICS genetic alterations in human tumor samples." (PMID 38463398, 2024). "Moreover, PAICS knockdown resulted in the inhibition of tumor growth and improved OS in a murine xenograft model." (PMID 38463398, 2024).
tumor (continued). "Furthermore, we conducted an in vivo study to affirm the impact of DYRK3 and PAICS on tumor growth and radiotherapy resistance, focusing particularly on the role of DYRK3 in the radiotherapy resistance pathway." (PMID 38139175, 2023). "Overall, CCNB1, CDK1, and PAICS could be three critical genes that influence tumor stage development of NSCLC and they could produce a poor prognosis." (PMID 36081668, 2022). "PAICS may promote the migration of tumour cells by increasing the number of clones and enhancing the adhesion ability." (PMID 34173716, 2021). "In tumor tissues, PAICS expression was found in the cytoplasm of tumor cells." (PMID 33596246, 2021). "Moreover, knockdown of PAICS significantly enhanced the growth inhibition of GC cells induced by CDDP treatment in the subcutaneous xenograft tumor model in vivo." (PMID 32632107, 2020). "Upon PAICS knockdown, there were also less tumor growth and lower tumor weights." (PMID 32218208, 2020). "Therefore, knockdown of PAICS significantly inhibited tumor growth in vivo." (PMID 38463398, 2024). "PAICS enhances DNPB flux by recruiting UBAP2, boosting nucleotide synthesis and tumor proliferation." (PMID 40699765, 2025). "Collectively, these results demonstrate that PAICS plays a pivotal role in regulating LUAD cell proliferation, clonogenicity, migration, and invasion, underscoring its potential as a key driver of tumor progression and a promising therapeutic target." (PMID 40699765, 2025). "In addition, through differential expression analysis on the cell types that predominantly occupy the tumor and muscle regions based on the deconvolution of eMCI, some key genes with spatial heterogeneity of spatial expression patterns were detected, such as PAICS, MITFA, SOX10, and COX6A2." (PMID 39494219, 2024). "Subsequent experiments using tumor samples from the xenograft mouse models revealed significant suppression of DYRK3, PAICS, and Ki-67 proteins in the mice treated with the DYRK3 inhibitor and the combined treatment, relative to the control mice." (PMID 38139175, 2023). "On the other hand, PAICS, activated in LADC tissues, was previously shown to function as a tumor-promoting gene." (PMID 35379785, 2022). "We also established that PAICS was involved in cellular growth, colony formation, invasion, and the spheroid-forming capacity of CRC cells as well as in tumor growth and metastasis in animals." (PMID 32218208, 2020). "To further investigate the impacts of MTHFD2 and PAICS on tumor aggressiveness, we analyzed the relationship of MTHFD2 and PAICS expressions with tumor stages (INSS)." (PMID 31624245, 2019). "A significant reduction both in tumor growth and weight was observed in both PPAT (respectively) and PAICS (respectively) knockdowns compared to the control cells, demonstrating that PPAT and PAICS play essential role in lung tumor growth in vivo." (PMID 26140362, 2015). "The third class of isolated yeast cell death suppressors includes molecules such as PAICS, STEAP1 and MALAT1, for which overexpression and/or functional relevance in tumor biology has been published." (PMID 23717670, 2013). "Our Oncomine database searches revealed an overexpression of PAICS, MALAT1 and MAST2 mRNA in various tumor entities." (PMID 23717670, 2013). "PAICS, an enzyme required for de novo purine biosynthesis, the long non-coding RNA MALAT1 and the MAST2 kinase are overexpressed in certain tumor entities and capable of suppressing apoptosis in human cells." (PMID 23717670, 2013). "Notably, PAICS and ATIC regulate critical steps in the G1-S transition and DNA replication, thus supporting rapid tumor growth." (PMID 40699765, 2025). "Although moderate to strong cytoplasmic PAICS immunoreactivity was commonly seen in the majority of tumor tissues, we found that some tumors showed no PAICS staining, which appeared to be comparable to that of non-tumor mucosa." (PMID 33596246, 2021).
tumor (continued). "When PAICS is inhibited, the NER pathway gene is up‐regulated and DNA repair capacity is enhanced, which may inhibit further tumour development." (PMID 34173716, 2021). "These morphological changes, together with the correlation of MTHFD2 or PAICS expression to INSS, led us to probe whether MTHFD2 and PAICS play roles in malignant transformation and tumor aggressiveness." (PMID 31624245, 2019). "A549 cells with stable knockdown of PPAT or PAICS showed reduction in CAM tumor growth compared to cells with non-targeting shRNA controls (respectively)." (PMID 26140362, 2015). "Collectively, our tumor expression analysis of PAICS, MALAT-1 and MAST2 confirmed the overexpression of all three genes in various tumor entities, thereby supporting the tumor relevance of candidate genes isolated by functional yeast survival screenings of tumor-derived cDNA libraries." (PMID 23717670, 2013). "Of 235 adjacent non-tumor tissues available for evaluation, only 30 (12.8%) were considered positive for PAICS expression, while 179 of 252 CRC tissues (71.0%) were found to be PAICS-positive (P<0.0001), further confirming the overexpression of PAICS in tumor at protein levels." (PMID 33596246, 2021). "Correspondingly, the similar findings were obtained in both the CIT cohort (r = -0.13, P<0.01) by Affymetrix microarray and the TCGA cohort (r = -0.11, P<0.01) based on RNA-seq, showing a weak but significant negative correlation between the expression of PAICS and tumor progression." (PMID 33596246, 2021). "We conducted qRT-PCR, microarray and RNA-seq analysis followed by immunohistochemistry and demonstrated that the expression of PAICS transcript and PAICS protein was significantly upregulated in the majority of tumor tissues, compared to that of non-tumor mucosa." (PMID 33596246, 2021). "Interestingly, the tumor cells quickly adapted to growth in the absence of PAICS, possibly by switching to the salvage pathway for purine biosynthesis." (PMID 23717670, 2013). "Our analysis shows that the levels of PAICS RNA and protein were elevated in most CRC tissues irrespective of tumor stage or patient race, gender, or age." (PMID 32218208, 2020). "Note that in the absence of tumor formation at day 3, the expression of PPAT, IMPDH1, IMPDH2, DHODH but not PAICS are all statistically significantly elevated with MYC induction." (PMID 18628958, 2008).
infection (5 papers, 2018 to 2023). The state of being infected such as from the introduction of a foreign agent such as serum, vaccine, antigenic substance or organism. "After infection with PAICS shRNA, MTT assays were performed on both cell types for 5 consecutive days." (PMID 30097015, 2018). "The mRNA level of PAICS was significantly reduced in both cell lines with siPAICS infection compared to expression in siCon-transduced cells." (PMID 30097015, 2018). "Thus, our analysis further validated the 3CLpro cleavage of NUP107 and PAICS during infection and identified four new high-confidence new candidate 3CLpro substrates in a dataset that included samples that were not enriched for neo-termini, thus validating our approach." (PMID 37240067, 2023).
adenocarcinoma (2 papers, 2015 to 2021). A common cancer characterized by the presence of malignant glandular cells. "Furthermore, our analysis showed that PPAT and PAICS are highly expressed in the solid type of adenocarcinoma." (PMID 26140362, 2015).
neurodevelopmental disorder (1 paper, 2025). A behavioral and cognitive disorder with onset during the developmental period that involves impaired or aberrant development of intellectual, motor, or social functions. "Our observation expands the clinical spectrum of PAICS deficiency from recurrent abortions and fatal neonatal form to later onset neurodevelopmental disorders." (PMID 39604553, 2025).
PAICS also shares sentences with these, for which no sentence is quoted: non-small cell lung carcinoma (3 papers); lymphoma (2); pancreatic cancer (2); breast invasive carcinoma (1); candidiasis (1); Cerebral ischemia (1); cervical squamous cell carcinoma (1); colon adenocarcinoma (1); colon adenoma (1); colon cancer (1); colorectal (1); diabetic retinopathy (1); diffuse large B-cell lymphoma (1); endocervical adenocarcinoma (1); esophageal cancer (1); folate deficiency (1); head and neck squamous cell carcinoma (1); infectious disease (1); invasive ductal carcinomas (1); ischemia (1); kidney chromophobe (1); large cell lung carcinoma (1); liver cancer (1); lymph node metastasis (1); mesothelioma (1); neurological disorders (1); prostate adenocarcinoma (1); sarcoma (1); SARS-CoV infection (1); thyroid carcinoma (1).